TTN (titin)
Diseases named in the same sentence as TTN in open-access papers (continued):
Sharing a sentence is not in itself a finding about the gene and the disease.
cardiomyopathy (continued). "Currently, genetic analysis of TTN for diagnosed or suspected cases involving cardiomyopathies should be performed because it is the main gene responsible for DCM." (PMID 26516846, 2015). "Nonetheless, these findings point toward an important epigenetic mechanism that could contribute to transcriptional reprogramming in TTN-related cardiomyopathies." (PMID 41283336, 2025). "Notably, alterations in TTN represent a valuable opportunity for developing targeted therapies for both genetic and acquired cardiomyopathies, offering hope for improved treatment options in these conditions." (PMID 41190030, 2025). "Mutations in the TTN gene (MIM: 188840) that encodes titin are related to a broad range of muscle diseases known as titinopathies, with diverse clinical manifestations including weakness, contractures, scoliosis, respiratory failure, and cardiomyopathy." (PMID 39926328, 2025). "It has been suggested that titin and MyBP-C aggregates can accumulate intracellularly and inhibit the ubiquitin–proteasome system, thereby disrupting protein quality control mechanisms in cardiomyopathies." (PMID 40725155, 2025). "Taken together, our findings suggest that TTN may contribute to a broader spectrum of cardiac phenotypes than traditionally recognized, including cardiomyopathies, primary electrical disorders, and conduction disease." (PMID 41465321, 2025). "The pivotal role of TTN in cardiomyopathies, together with the emerging importance of epigenetic regulation, raises the possibility that the interplay between TTN and HDAC5 could provide new insights into disease pathogenesis." (PMID 41283336, 2025). "While the role of the TTN gene in cardiomyopathy has been extensively studied, its function in cancer remains unclear." (PMID 39748197, 2025). "The giant protein titin (TTN) is a sarcomeric protein that forms the myofibrillar backbone for the components of the contractile machinery which plays a crucial role in muscle disorders and cardiomyopathies." (PMID 38438525, 2024). "ACM-causing mutations have also been identified in genes outside the desmosome, including phospholamban (PLN), filamin C (FLNC), desmin (DES), titin (TTN), and lamin A/C (LMNA), which are linked with other cardiomyopathies, including DCM and neuromuscular cardiomyopathies." (PMID 38610600, 2024). "TTN c.13254T>G leads to an earlier termination of translation at amino acids 4418, which highly likely results in the expression of the truncating protein, and cardiomyopathy." (PMID 38381767, 2024). "Furthermore, mutations in genes like TTN, TNNI3, and TNNT2 have been associated with a spectrum of cardiomyopathies, reflecting the complexity of genetic influences on cardiac function and structure." (PMID 38893676, 2024). "One study of 223 HCM patients found that ∼ 61% of patients harboured rare titin missense variants, with 19% having these without co-inheriting variants in any other candidate cardiomyopathy disease genes." (PMID 37549721, 2023). "Furthermore, advances in high-frequency echocardiographic imaging techniques have opened new avenues for using adult zebrafish to model adult-onset cardiomyopathies, such as titin-related DCM." (PMID 37887855, 2023). "This includes non-ischemic DCM, which is the most common form of cardiomyopathy and originates in 25% of the cases from truncation mutations in TTN." (PMID 35741855, 2022). "Two PV/LPVs related to cardiomyopathy were detected in the TTN and MYH7 genes." (PMID 36005429, 2022). "Mitochondrial therapies might be particularly effective in titin truncation cardiomyopathy more so than in other cardiomyopathies, though this is yet to be fully elucidated." (PMID 36671398, 2022). "Two patients (15 and 16) with the missense variant but not the truncating variant expressed in the N2B isoform of titin have been diagnosed with a cardiomyopathy." (PMID 33449170, 2021).
cardiomyopathy (continued). "It should be noted, however, that cardiomyopathy is not a consistent feature for dominantly-inherited HMERF mutations in the Fn3-119 domain, which is expressed in all titin transcripts." (PMID 33449170, 2021). "Furthermore, FHL2 is involved in sarcomere integrity, partly through interaction with actin and titin, and FHL2 mutations are associated with both dilated and hypertrophic cardiomyopathy, and FHL2 is thus believed to contain cardioprotective properties." (PMID 33716758, 2021). "This suggests a two hit hypothesis for development of TTNtv cardiomyopathy where TTN haploinsufficiency increases metabolic stress and when combined with additional risks such as age, toxins, pregnancy or acquired disease can lead to development of DCM." (PMID 32859027, 2020). "The TTN gene, which encodes a large abundant protein of striated muscle containing cardiac muscle tissues, is involved in the DCM and HCM pathways, and it has been reported as one of the positively selected genes that influence cardiomyopathy in a bear breed." (PMID 31440273, 2019). "A defect of the MLP/TCAP/TTN complex may lead to the development of cardiomyopathy and heart failure." (PMID 30995779, 2019). "Dilated cardiomyopathy-linked mutations in TTN and other sarcomeric proteins as well as with no found mutations decrease titin elasticity characterized by a decrease in myofibrillar stiffness by about 26%." (PMID 30065175, 2018). "However, the current study provides preliminary information regarding TTN Novex splicing and their potential function in cardiomyopathies." (PMID 29438341, 2018). "Missense variation in TTN is common, and although some individual variants cause cardiomyopathy, it is not currently possible to interpret the DCM risk associated with the vast majority of these variants." (PMID 29691892, 2018). "In this review we discuss selected examples of cardiomyopathy genes (TTN, FHL1, CSRP3, FLNC and PLN) which, based on their known biological functions and the (limited) functional work on the disease-causing pathogenic variants, have been shown to have important signalling functions in the heart." (PMID 29119312, 2017). "Other studies demonstrate that TTN is frequently mis-spliced in cardiomyopathy." (PMID 28098235, 2017). "In addition to TTN and BAG3, MYBPC3 was present in the cardiomyopathy gene-set and harbored variants associated with sporadic DCM in our EWAS." (PMID 28296976, 2017). "With exception of TTN truncating variants in DCM, the pathogenic variants in the genes discussed here are individually rare, but collectively they contribute to an estimated 3% of cases in cardiomyopathy cohorts." (PMID 29119312, 2017). "Consequently, genetic screening of the titin gene (TTN) is clinically relevant in most cardiomyopathy cases." (PMID 27683155, 2016). "This expands the spectrum of titin’s roles in cardiomyopathies." (PMID 27625337, 2016). "Furthermore, TTN is involved in the pathogenesis of other cardiomyopathies such as HCM and ARVC that is considered to be a genetic disease (30–50% of cases are familial), and RCM." (PMID 27493940, 2016). "These impaired mechanisms of thin-filament activation and tension production may contribute to cardiac dysfunction and the associated cardiomyopathies in humans, rats, and mice bearing RBM20 mutations that influence titin splicing." (PMID 27524973, 2016). "One identified titin mutation, p.E10320X, was located in the PEVK region, which was previously confirmed to contribute to the elastic properties of the cardiac ventricle and thus probably lead to cardiomyopathy with diastolic dysfunction." (PMID 26573135, 2015). "Recently, more extensive genetic analysis in families with both dilated cardiomyopathy and peripartum cardiomyopathy from various parts of the world revealed a high yield of mutations in cardiomyopathy-related genes, especially in TTN, the gene encoding for titin." (PMID 25007941, 2014).
cardiomyopathy (continued). "A pan cardiomyopathy microarray designed to identify mutations in genes associated with cardiomyopathy and CPVT revealed three mutations: ryanodine receptor (RyR2) Arg169Gln, calsequestron (CASQ2) Asp398del, and titin (TTN) Lys4455Arg." (PMID 23476865, 2013). "Hence, mutations in some genes involved in this area, such as titin and titin-cap, can result in cardiomyopathy." (PMID 20515474, 2010). "Emerging evidence suggests that genetic variants, particularly those affecting the sodium and potassium channels, cardiomyopathy-related genes (such as TTN), gap junction channels, and transcription factors, may contribute to the development of AF in younger populations." (PMID 39336546, 2024). "Beyond cardiomyopathies, TTN mutations are implicated in numerous non-cardiac muscle disorders." (PMID 38438525, 2024). "TTN truncating variants have been suggested to cause 25% of DCM, and the MYH7 gene, related to sarcomeres, may be present with a spectrum of phenotypical cardiomyopathies [HCM, DCM])." (PMID 36005429, 2022). "Whether or not TTN truncating variants cause cardiomyopathy has been proven, to some extent, to depend on the region of the TTN protein where the mutation is located." (PMID 33928132, 2021). "As RBM20 functions in the pre-mRNA splicing of the TTN gene, which provides connections at the level of individual microfilaments, loss of RBM20 inhibits muscle differentiation and leads to heart diseases such as cardiomyopathy and ischemic heart disease in vivo." (PMID 33789631, 2021). "Indeed, heterozygous truncating variants in TTN have been mainly implicated in cardiomyopathy without skeletal muscle involvement." (PMID 34440373, 2021). "Therefore iPSC-CM emerge as a novel model system to study titin-related cardiomyopathy." (PMID 31147888, 2019). "Lastly, the practicability of using a urinary biomarker may be limited for the perioperative course of cardiac operations because urinary titin measurements cannot be applied to patients with renal dysfunction after prolonged cardiomyopathy bypass or to those with renal failure." (PMID 30800662, 2019). "The involvement of TTN mutations, and especially of TTNtv in the pathogenesis of cardiomyopathies, have been known for more than a decade, but the lack of sophisticated sequencing techniques has not allowed the identification and population prevalence of TTNtv in large cohorts." (PMID 28510119, 2017). "Three of the DCM-associated genes, FLNC, TTN (through its kinase activity) and cardiac specific FHOD3 encode maintenance partners of sarcomere and sarcomere-related structures, including Z-disk or F-actin myofibrils, which are disorganized or degraded in experimental models of cardiomyopathy." (PMID 28296976, 2017). "Titin (TTN) is a sarcomeric protein that forms the myofibrillar skeleton and regulates muscle disorders and cardiomyopathy." (PMID 40264452, 2025). "For example, a type of cardiomyopathy can be influenced by both titin haploinsufficiency (LOF) and truncated titin peptides that seem to “poison” wild-type complexes (DN)." (PMID 39172982, 2024). "Almost every discordant variation is found on either the TTN gene (83 variations) or the Antisense TTN gene (TTN-AS1, 52 variations), both of which are well-known cardiomyopathy-related genes." (PMID 37946154, 2023). "Endothelin signaling was activated in LMNA mutant cardiomyopathy, whereas IL6 signaling was activated in TTN mutant cardiomyopathy." (PMID 36950287, 2023). "Overall, lead variants at 9 of the 61 GWS loci were located nearest to known cardiomyopathy genes (ACTN2, ALPK3, BAG3, FLNC, PLN, TTN), representing significant enrichment (hypergeometric p = 6.01 × 10−11)." (PMID 36376295, 2022).
cardiomyopathy (continued). "Despite extensive interest in titin and strong acknowledgement of the prevalence of TTNtv in DCM, the mechanism of the involvement of TTNtv in cardiomyopathy is still unclear." (PMID 33135063, 2022). "Titin (TTN) is the largest sarcomeric protein found in the heart and is involved in the pathophysiology of cardiomyopathy." (PMID 34154667, 2021). "We uncovered genomic regions of selective sweeps in the LBP and BPI genes (Salmonella infection) and the TTN and ITGB6 genes (cardiomyopathy), among several candidate genes." (PMID 31440273, 2019). "We identified genes with alternative splicing profiles that were common to cardiomyopathy (PDLIM3, CD36, CLDND1, TTN, FAM126a, TLR4, and CD59)." (PMID 28098235, 2017). "Despite the graveness of titin-related cardiomyopathies, the molecular mechanisms of titin and its roles in cardiomyopathies remain complex and not fully understood." (PMID 36147537, 2022). "Therefore, we further investigated patterns of nucleotide diversity, linkage disequilibrium, haplotype diversity, and Fst of LBP, BPI, ITGB6, and TTN genes, among KNG’s candidate genes enriched in Salmonella infection and cardiomyopathy pathways." (PMID 31440273, 2019). "We have demonstrated with the examples of Titin, FHL1, MLP/Csrp3, Filamin C and Phospholamban discussed here, that there are disease genes for cardiomyopathies beyond the “classical” genes coding for proteins with exclusively structural roles in the sarcomere or the cytoskeleton." (PMID 29119312, 2017). "Additional cluster 3 proteins categorized to cardiomyopathy and sarcomeric proteins exposed to constant mechanical stress, including Desmin (DES), dystrophin muscular dystrophy (DMD); myosin binding protein C, cardiac (MYBPC3); myosin light polypeptide 2 (MYL2); Titin (TTN) and phospholamban (PLN)." (PMID 36681760, 2023). "While most research on RBM20 splicing targets has focused on titin (TTN), multiple studies over the last years have shown that other splicing targets of RBM20 including Ca2+/calmodulin-dependent kinase IIδ (CAMK2D) might be critically involved in the development of RBM20 cardiomyopathy." (PMID 32789749, 2020). "TTN mutations are associated with cardiac diseases, particularly dilated cardiomyopathy (DCM) that presents with ventricular enlargement and systolic dysfunction in the absence of alternative etiologies of cardiomyopathy such as valvular, hypertensive, congenital, or ischemic causes." (PMID 31849696, 2019).
dilated cardiomyopathy (157 papers, 2007 to 2026). Cardiomyopathy which is characterized by dilation and contractile dysfunction of the left and right ventricles. "Germline TTN mutations are strongly linked to dilated cardiomyopathy and arrhythmias, and emerging evidence suggests a possible relationship between TTN alterations and oncologic processes." (PMID 41883887, 2026). "The most frequently mutated genes related to dilated cardiomyopathy (DCM) were TTN, MYH7, NEXN, TNNI3, and SCN5A." (PMID 41341110, 2025). "In dilated cardiomyopathy, however, the most frequently mutated gene is TTN, present in 20%–25% of patients." (PMID 41019439, 2025). "Truncated mutants of titin are structurally incorporated in the sarcomere and cause axial disintegration, thereby leading to the pathogenesis of dilated cardiomyopathy." (PMID 37962957, 2024). "First, we used CASAAV-HDR to create and study two frameshifting titin variants that result in protein truncation and dilated cardiomyopathy in humans." (PMID 39677651, 2024). "A cohort study related to women with dilated cardiomyopathies in peripartum revealed that 83 of the patients who presented with lower EF at the one-year follow-up had a concurrent mutated titin (TTN) gene (p=0.005)." (PMID 38975458, 2024). "This case report details the identification of a novel likely pathogenic splicing variant in the TTN gene, associated with dilated cardiomyopathy (DCM), in a 42-year-old male patient presenting with early-onset heart failure and reduced ejection fraction." (PMID 38938651, 2024). "Heterozygous (HET) truncating variant mutations in the TTN gene (TTNtvs), encoding the giant titin protein, are the most common genetic cause of dilated cardiomyopathy (DCM)." (PMID 37962957, 2024). "Truncating mutations in the TTN gene are common genetic causes of dilated cardiomyopathy, leading to ventricular dilation and impaired contractile function." (PMID 39132134, 2024). "A phase 2a study aiming at establishing safety and preliminary efficacy of danicamtiv in patients with primary dilated cardiomyopathy (DCM) due to MYH7 or TTN variants." (PMID 37332581, 2023). "TTN mutations have been found to be associated with various diseases including dilated cardiomyopathy, centronuclear myopathy, and squamous cell carcinoma of the lung, among others." (PMID 36895786, 2023). "This includes the IGFBP5 gene candidate variant for bald thigh syndrome in sighthounds, SLC7A9 and SLC3A1 gene variants associated with cystinuria in Bulldogs, as well as PDK4 and TTN gene risk variants for dilated cardiomyopathy (DCM) in Dobermans." (PMID 36848397, 2023). "TTN mutations cause dilated cardiomyopathy and are associated with other left-sided congenital lesions." (PMID 37961530, 2023). "Specifically, pediatric patients had more MYH7 and MYL3 variants in hypertrophic cardiomyopathy, and fewer TTN truncating variants in dilated cardiomyopathy." (PMID 37477868, 2023). "TTN has high expression levels in the heart and artery systems, the missense variants of which cause dilated cardiomyopathy." (PMID 37888120, 2023). "Both BAG3 and TTN contribute to the function of the contractile apparatus in cardiomyocytes, and rare deleterious variations cause Mendelian forms of dilated cardiomyopathy." (PMID 35132965, 2022). "TTN can cause dilated cardiomyopathy (DCM) and a heterozygous truncated variant is the most common genetic cause of familial DCM." (PMID 36005429, 2022). "Monoallelic truncating variants in TTN (TTNtvs) predispose to dilated cardiomyopathy (DCM) in adults." (PMID 36761691, 2022). "Approximately 30% of patients with dilated cardiomyopathy were correlated with the TTN mutations, and only 1% of patients with HCM had mutations localized in TTN." (PMID 36304977, 2022). "Variants in TTN are associated with a broad range of clinical phenotypes, from dominant adult-onset dilated cardiomyopathy to recessive infantile-onset myopathy." (PMID 36761691, 2022).